CD44 (CD44 molecule (IN blood group))
Diseases named in the same sentence as CD44 in open-access papers (continued):
Sharing a sentence is not in itself a finding about the gene and the disease.
breast tumors (continued). "In this study, NIH-3T3 (CD44-) and 4T1 (CD44+) cell lines were used to evaluate the anticancer potential of the developed formulation against breast tumors." (PMID 32982750, 2020). "ALDH1 positive cells encompassed only a minor (about 1.2%), but highly tumorigenic population of CD44+/CD24−/low primary breast tumor cells." (PMID 32430004, 2020). "Fillmore and Kuperwasser suggested that CD44+ BCSCs are found in basal-like breast tumours, which have a poor prognosis." (PMID 31728117, 2019). "ARHGEF binds to CD44 protein, resulting in cytokine production and breast tumor progression, whereas CD44 binds to FAK in the context of cellular activation in Hela-CD4 cells." (PMID 31501460, 2019). "Further characterization of the CD24−/CD44+ BCSC-like subset with other stem cell markers revealed that estrogen-induced breast tumor initiating/cancer stem cells acquire additional phenotypes, such as 49f, EpCam, ALDH1, and CD133." (PMID 30486409, 2018). "Patients with triple negative breast cancer (ER−/PR−/HER2−) express CD44+CD49f+CD133/2 in breast tumor tissues, which positively correlate with a stem-cell-derived tumorigenic signature." (PMID 30486409, 2018). "In breast tumor cells, HA activation of CD44 leads to the expression of multidrug resistance gene (P-glycoprotein) and anti-apoptotic gene Bcl expression, which promotes tumor cell proliferation and survival." (PMID 29747682, 2018). "CD44-positive breast tumor cells (MDA-MB-231) exhibited more efficient internalization of the HA-coated nanoparticles compared with CD44-null normal cells (NIH3T3, CV-1)." (PMID 29747682, 2018). "The level of CD44 in the breast tumor cell lines CAMA-1, MDA-MB-231, MDA-MB-435 and the immortalized normal luminal cell line 226LDM was higher than that of CD74." (PMID 29190904, 2017). "Both immune-sorting and aldefluor assays revealed that human breast tumors harboured a higher population of both CD44+/CD24− and ALDH+ (aldehyde dehydrogenasehigh) cells (p < 0.001), compared to normal tissues." (PMID 28835684, 2017). "Use of a novel and validated colocalisation and image processing approach, coupled with co-immunoprecipitation, confirmed that CD74 and CD44 physically interact, suggesting a possible role in breast tumour growth." (PMID 29190904, 2017). "A previous study demonstrated that CD44+/CD24−/ESA+ was 50-fold enriched in the ability to form breast tumors relative to unfractionated tumor cells." (PMID 29197410, 2017). "We have previously reported that CD44 induction enhances the invasiveness of BC cell lines in vitro, and induced breast tumor metastasis to the liver." (PMID 29121955, 2017). "Our research efforts have been focused on understanding the mechanisms by which CD44 promotes breast tumor invasion." (PMID 29121955, 2017). "In contrast, the breast tumor sample contained high levels (3+) of CD44 expression with the concomitant low (1+) CD146 expression levels, and these findings were consistent with our Western blotting results." (PMID 29121955, 2017). "According to the analysis of 448 primary breast tumors, CD44 was parallel with enhancive distant recurrence and decreased disease-free survival." (PMID 28659634, 2017). "For example, upon binding with HA, CD44 interacts with TGFβ receptor I, resulting in the activation of TGFβ1 signaling in metastatic breast tumor cells." (PMID 28002484, 2016). "Purified CD44+CD24−/low breast tumor cells are capable of generating phenotypically distinct cells resulting in heterogeneous tumors in immunodeficient mice." (PMID 27070574, 2016). "Other researchers also showed that breast tumors express CD44 and CD24 but are very heterogeneous among different tumors and also within the tumor." (PMID 26968831, 2016). "The neurogenes HRH1 and NRP2 were upregulated in basal-related breast tumors and CD44+ cancer cells and another, STX1A, was upregulated in luminal B and HER2-enriched tumors." (PMID 26673618, 2016).
breast tumors (continued). "Twist overexpression promotes a cancer stem cell (CSC) phenotype and has also been shown to induce miR-10b, which inhibits the mRNA of HOXD10 and results in the increase of RhoC in CD44-positive breast tumor cells." (PMID 27070574, 2016). "Recently, it has been shown that the binding of HA to breast tumor cells promotes CD44-Nanog complex formation followed by the activation of miRNA signaling." (PMID 27070574, 2016). "For T47D cells, a breast tumor cell line, we used double CD44+/CD24− staining, which has been extensively used to identify cancer stem cells." (PMID 27613838, 2016). "The data presented in this study indicated that the stem-like sub-population, characterized by the CD44+/CD24low/− phenotype is the major contributor to bone and lymph node metastasis in Luminal-A breast tumors." (PMID 27835603, 2016). "The importance of CD44 in promoting the colonization of bone by breast tumor cells is further supported by our in vitro experiments." (PMID 25888636, 2015). "The ESA+CD44+CD24−/low lineage cells isolated from human breast tumors were able to form tumors in eight-week-old NOD/SCID mice." (PMID 25905435, 2015). "In a recent study, LMWHA (but not HMWHA) was found to preferentially stimulate a physical association between CD44 and TLRs followed by a concomitant recruitment of AFAP-110 and MyD88 into receptor-containing complexes in breast tumor cells." (PMID 25926834, 2015). "CD44-active breast tumor cells (MDA-MB-231) exhibited more efficient internalization of the HA-coated nanoparticles compared with CD44-inactive normal cells (NIH3T3, CV-1)." (PMID 25909172, 2015). "The results indicate that breast tumor cells (MDA-MB-231) with active CD44 appeared more sensitive to the cytotoxic activity of HA-coated nanoparticles than CD44-inactive normal cells (CV-1)." (PMID 25909172, 2015). "Shipitsin and colleagues have shown that TGF-β1 and the TGF-β type I receptor are overexpressed in CD44+ cells within breast tumors." (PMID 24581230, 2014). "Significantly, it has been demonstrated that treatment of breast tumors with conventional chemotherapeutic agents enriched the CD44+/CD24low/− subpopulation conferring resistance to the initial treatment and leading to the development of distant metastases." (PMID 24970653, 2014). "Here, various markers have been utilized in the detection of CSC population within breast tumor cells, such as sphere forming assay, CD44 and CD24 cell surface markers, PKH fluorescent dye, and expression of pluripotency markers." (PMID 25380486, 2014). "The gene signatures for the Luminal B-phenotype (β = 1.771; P<0.001) and CD44+ breast tumour cells (β = 2.009; P<0.001) demonstrate the opposite pattern." (PMID 24586640, 2014). "Breast tumor sections stained with three antibodies, 2A6, 2B12, and 2G10, also demonstrated unique CD44 staining patterns." (PMID 25353955, 2014). "Together, these findings strongly indicate that HA/CD44-activated JNK/c-Jun signaling plays an important role in the production of miR-21 in breast tumor cells." (PMID 24606718, 2014). "HA binds specifically to CD44, a family of multifunctional transmembrane glycoproteins expressed in numerous cells and tissues, including breast tumor cells and various carcinoma tissues." (PMID 24606718, 2014). "Chang and his colleagues have showed that increased EZH2 expression in CD44+ /CD24-/low breast tumor initiating cells correlated with the increased percentage of this specific subpopulation." (PMID 24345883, 2013). "As cited before, CSCs are identified as CD44+ CD24−/low in breast tumors while, in gliomas, they have been identified mostly on the basis of the expression of CD133 (or prominin 1)." (PMID 23476653, 2013). "TN aggressive human breast tumors as well as transplantable xenografts obtained from SKBR3 expressed significantly lower levels of VDR but higher levels of CD44 expression." (PMID 23341935, 2013).
breast tumors (continued). "On the other hand, claudin-3, a tight junction protein depleted in CD44+/CD24- CSC enriched basal/mesenchymal breast tumors, was among the most down regulated genes in SK-β1-C1." (PMID 23991019, 2013). "The CD44+/CD24− cells were found in 91% of breast tumours and constituted an average of 6.12% (range, 0.11%–21.23%) of the tumour." (PMID 23028444, 2012). "In breast tumors, a CD44+CD24–/lowESA+ lineage subpopulation was originally identified as the tumorigenic (tumor-initiating) fraction." (PMID 22901246, 2012). "We observed variations in the prevalence of CD44+/CD24- tumor cells in breast tumors of different subtypes." (PMID 22762532, 2012). "Here, we demonstrated that multiple immunofluorescence coupled with confocal microscopy analysis is a simple and reliable method to identify CD44+/CD24− cells in routine surgical breast tumour samples." (PMID 23028444, 2012). "CD44 signaling is involved in underpinning breast tumor invasion, thereby promoting breast tumor invasion and metastasis to the liver." (PMID 22634835, 2012). "To evaluate the relationship between BRCA1 expression and the breast CSC marker CD44, we correlated the cytoplasmic and nuclear expressions of BRCA1 with the level of expression of CD44 obtained from our previous study in the same series of breast tumours." (PMID 23508738, 2011). "The relationship between hypoxia markers and CD44+CD24-/low immunophenotype in breast tumors still poorly understood." (PMID 21824412, 2011). "Similar to the claudin-low category of breast tumors, the CD44+ breast tumor cells also express low levels of differentiation specific markers." (PMID 22028892, 2011). "In breast tumors, CD44+ cells from both primary tumors and lung metastases are highly enriched for tumor-initiating cells." (PMID 24212663, 2011). "We used q-RT-PCR and exon-exon spanning assays to analyze the expression of four alternatively spliced CD44 isoforms as well as the total expression of CD44 in 187 breast tumors and 13 cell lines." (PMID 21957977, 2011). "The pattern of BRCA1 expression was then correlated with expression of CD44 (CD44+ cancer stem cell phenotype) in the same collection of breast tumours." (PMID 23508738, 2011). "Breast tumors expressing CD44+CD24-/low immunophenotype showed relationship with HIF-1α (p = 0.039) and negativity for HER-2 (p = 0.013)." (PMID 21824412, 2011). "CD44 is a useful marker for collecting CSCs not only in breast tumors but also in a variety of other tumor models." (PMID 24212663, 2011). "Breast tumors that contained higher proportion of BT-ICs with CD44+/CD24− phenotype, ALDH1 enzymatic activity and sphere forming capacity were more resistant to neoadjuvant chemotherapy." (PMID 21187973, 2010). "Numerous isoforms of CD44 exist, and some of them are overexpressed on breast tumour cells which seems to be correlated with the metastatic potential." (PMID 20565761, 2010). "In human breast tumors, the CD44+/CD24-/low phenotype has been reported to have stem cell properties." (PMID 20696077, 2010). "Another study on paraffin-embedded breast tumors revealed that the CD44+/CD24low/- phenotype is most common in the basal subtype and particularly common in BRCA1 hereditary tumors, of which 94% contained CD44+/CD24low/- cells." (PMID 19555472, 2009). "Most current studies have emphasized the identification of cancer stem cell subpopulations from breast tumors using CD44 and CD24." (PMID 20027313, 2009). "In bone marrow specimens of 50 patients with early breast tumors, CD44+/CD24low/- phenotype in cytokeratin-positive cells was detected in 72% of all disseminated tumor cells (DTC) compared with less than 10% in primary tumors." (PMID 19555472, 2009). "Our results demonstrate a clear variation in the prevalence of CD44+/CD24- tumor cells between breast tumors of different subtypes." (PMID 18559090, 2008). "Cells from primary human breast tumors with a CD44+/CD24-/low phenotype enrich for tumor formation in vivo." (PMID 18366788, 2008).
breast tumors (continued). "A CD44+ CD24low/- population was isolated from breast tumours and pleural effusions by Al-Hajj and colleagues and these cells were found to be enriched with tumorigenic cells." (PMID 18541018, 2008). "Recently it was reported that breast tumors from patients treated with chemotherapy contained higher proportion of CD44+, CD24low cells with CSC properties than breast tumors from untreated patients." (PMID 18728788, 2008). "Detection of CD44-overexpressing breast tumors may offer valuable insights into selecting the most effective therapeutic strategies, as well as into predicting disease progression and treatment responsiveness." (PMID 40468893, 2025). "The free HA could bind with theHA receptor (CD44) in breast tumors, which could competitively inhibitthe binding between NP-ICG-HA and CD44 in tumors." (PMID 38757711, 2024). "In the current study, using CD44 neutralizing antibodies significantly decreases iron content in breast tumor cells but this could also be subject to indirect impact on cellular proliferation and survival." (PMID 39201626, 2024). "Furthermore, IHC examination exhibited that the mice anti‐CD44 polyclonal Ab, like typical anti‐CD44 monoclonal Ab, can detect CD44 protein expressed in breast tumors." (PMID 36289579, 2023). "These CD44‐mediated clusters form within the vasculature in the primary tumor, and are then observed in lung metastases, suggesting that CD44 directs the aggregation of individual detached breast tumor cells that enhances metastasis." (PMID 37492150, 2023). "Finally, we investigated the interactions between the HA-based cryogels and CD44-positive breast tumor cells, individually or as MCTS." (PMID 35198956, 2022). "The CD44+/CD24 low/− population has been isolated from the primary breast tumors." (PMID 36585652, 2022). "Notably, also the percentage of CD44+/CD24−/low cells can be modulated in breast tumor cell lines by altering glutamine concentration in culture medium." (PMID 34492636, 2021). "Notably, there was a very good correlation between the inclusion of CD44 variant exons and the local levels of meDNA in three different cell types : HCT116/DKO, DNMT1-depleted HeLa cells and MCF10A-derived breast tumor cells." (PMID 34086943, 2021). "CD44 is a useful marker for collecting CSCs not only in breast tumors but also in a variety of other tumor models; CD44 may also be important in metastasis." (PMID 32684928, 2020). "Intriguingly, 100% of CD44+ breast tumor cells are positive for ProCr." (PMID 33234169, 2020). "Notably, the analysis of post-operative vs. pre-operative breast tumor specimens showed a selective reduction in the stem markers, namely CD44 and ALDH1, in the patients receiving Doxycycline compared with controls." (PMID 31440463, 2019). "Thus, genistein, a predominant isoflavone found in soy products, has been reported to decrease the CD44/CD24-positive CSC population in MCF7 breast tumor cells and mammosphere formation by downregulating Hedgehog-Gli1 signaling pathway." (PMID 28156178, 2017). "Treatment of CD44+/CD24− BCSCs derived from breast tumor tissues with formestane, an aromatase inhibitor, results in a 16% (p < 0.01) decrease in cell proliferation in response to single-agent trastuzumab and 50% decrease (p < 0.001) in response to combined trastuzumab and formestane treatment." (PMID 28445439, 2017). "To investigate whether CD326− CD44+ adherent fibroblasts express mesenchyme-derived surface markers, we performed immunophenotypic characterization of the monolayer generated in breast tumor fragment cultures after 3 weeks by flow cytometry." (PMID 28649646, 2017). "However, expression of CD44 in human breast tumors is correlated with both favourable and unfavourable clinical outcomes." (PMID 29190904, 2017).
breast tumors (continued). "In this study, we focused on the intratumor morphological heterogeneity in IC NST, performed 3D imaging, whole genome copy-number and transcriptome profiling of the different morphological structures of breast tumors and analyzed the distribution of CD44+CD24- CSCs." (PMID 28977854, 2017). "However, recent studies suggest that there are several distinct CSC sub-populations in breast tumors, one is characterized by the CD44+/CD24low/− phenotype, and the other by ALDH1+." (PMID 27835603, 2016). "In line with other studies, the CD44+/CD24low/− sub-population comprised only ~1% of the original Luminal-A breast tumor cells, but we demonstrated that the proportion of these cells was profoundly increased by TME Stimulation (to ~15% or ~5%, in MCF-7 and T47D cells, respectively)." (PMID 27835603, 2016). "Indeed, in this study we demonstrate that the combined TME Stimulation by estrogen+TNFα+EGF has enriched Luminal-A breast tumor cells not only for the CD44+/β1+ sub-population, but also for the CD44+/CD24low/− sub-population." (PMID 27835603, 2016). "Indeed, basal-like breast tumors, which are enriched for CD44+/CD24− cells, exhibit epithelial–mesenchymal transition features and express high levels of stem cell-regulatory genes." (PMID 26556856, 2016). "CD44 was predominantly expressed on the plasma membrane of breast tumor epithelial cells." (PMID 25888636, 2015). "CD44 is known to stimulate breast tumor cell invasion through the RhoA pathway." (PMID 25840418, 2015). "In addition, further examination revealed that alterations of CD44 states can occur within the breast tumor microenvironment." (PMID 25909172, 2015). "More recently, HA staining and CD44 expression have been examined in HER2-positive breast tumors." (PMID 26106384, 2015). "For this purpose, we purified bCSCs flow-cytometrically from primary breast tumors on the basis of the cell surface phenotype CD44+/CD24-/low and confirmed their stemness properties on the basis of the expression levels of the following markers: MRP1 and ABCG2, ALDH1, and Oct-4, Sox-2, and Nanog." (PMID 25315241, 2014). "Even within breast tumors, the accepted combination of surface markers CD44/CD24 shows differences among different subtypes, being the CD44+/CD24− phenotype common in the basal subtype, specially in BRCA1 hereditary tumors, but surprisingly scarce in HER2-positive tumors." (PMID 25414831, 2014). "As few as 200 CD44+CD24−/lowlin− cells have been reported to be able to generate a breast tumor." (PMID 24331293, 2013). "Breast tumour-initiating stem cells (T-ISC) are known to be enriched in CD44+CD24neg/low cells." (PMID 23982961, 2013). "Recent studies have identified that TNBC breast tumors may also have a higher content of CD44+/CD24- cells." (PMID 24167614, 2013). "In breast tumors, a population of cells enriched in markers CD44+ CD24−/low was identified as CSCs." (PMID 23476653, 2013). "The culture of MCF-7 cells under these conditions resulted in the formation of mammospheres that were then trypsinized, disaggregated and analyzed by flow cytometry showing an enrichment in CD44+/CD24low/- cells, a phenotypic characteristic that is considered a marker of CSCs in breast tumors." (PMID 23216744, 2012). "Subsequently, CD24 and CD44 were selected as CSC markers in breast tumors." (PMID 22359637, 2012). "It is possible that breast tumors with inherently low CD44 expression may show a more dramatic increase in CD44 expression in hypoxic regions compared to normoxic regions." (PMID 22937154, 2012). "Here we demonstrated that CD44+CD24-/low breast tumors show an association with HIF-1α status, but not with CAIX." (PMID 21824412, 2011). "There are evidence that hypoxia could drive the maintenance of CSC, via HIF-1α expression, but it still to be determined whether hypoxia markers are expressed in breast tumors presenting CD44+CD24-/low immunophenotype." (PMID 21824412, 2011).